TUBG2 (tubulin gamma 2)
Description:
Tubulin is the major constituent of microtubules, protein filaments consisting of alpha- and beta-tubulin heterodimers. Gamma-tubulin is a key component of the gamma-tubulin ring complex (gTuRC) which mediates microtubule nucleation. The gTuRC regulates the minus-end nucleation of alpha-beta tubulin heterodimers that grow into microtubule protafilaments, a critical step in centrosome duplication and spindle formation.
Tractability: Small molecule: it belongs to a druggable protein family. PROTAC: ubiquitination databases record sites on it.
Gene: Protein-coding gene on chromosome 17 (42,659,223 to 42,667,007, forward strand). Ensembl gene ENSG00000037042.
Subcellular location: Cytoplasm, cytoskeleton, microtubule organizing center, centrosome
Subcellular location (Human Protein Atlas): Centriolar satellite; Principal piece
Pathways (Reactome):
Cell Cycle: Recruitment of NuMA to mitotic centrosomes; Recruitment of mitotic centrosome proteins and complexes
Gene Ontology:
Molecular function: GTP binding; microtubule nucleator activity; structural molecule activity
Biological process: meiotic spindle organization; mitotic cell cycle; mitotic sister chromatid segregation; mitotic spindle organization; cytoplasmic microtubule organization; microtubule nucleation; microtubule-based process
Cellular component: centriolar satellite; microtubule; centrosome; cytosol; gamma-tubulin ring complex; microtubule cytoskeleton; spindle; cytoplasmic microtubule; gamma-tubulin complex; microtubule organizing center; pericentriolar material; spindle microtubule
Genetic constraint (gnomAD): Loss-of-function variants: 39 observed, 56.41 expected, observed/expected ratio (o/e) 0.69, 90% interval 0.53 to 0.9. The upper end of that interval is the gene's LOEUF score, 0.9, which puts it in group 3 of 6, group 1 being the genes least tolerant of losing a copy. Missense variants: 358 observed, 607.32 expected, observed/expected ratio (o/e) 0.59, 90% interval 0.54 to 0.64. Synonymous variants: 223 observed, 240.9 expected, observed/expected ratio (o/e) 0.93, 90% interval 0.83 to 1.03.
Homologues: Orthologues: chimpanzee TUBG2 (100% identical), pig TUBG2 (98% identical), dog TUBG2 (98% identical), guinea pig TUBG2 (98% identical), mouse Tubg2 (98% identical), rat Tubg1 (88% identical). Paralogues in human: TUBG1 (98% identical), TUBB4B (35% identical), TUBB8 (35% identical), TUBB8B (35% identical), TUBB3 (35% identical), TUBB2A (35% identical), TUBB2B (35% identical), TUBB4A (35% identical), TUBB (35% identical), TUBB6 (35% identical), TUBB1 (33% identical), TUBA1C (31% identical), and 11 more.
Diseases named in the same sentence as TUBG2 in open-access papers:
TUBG2 is named in the same sentence as 15 diseases in open-access papers, as found by Europe PMC text mining. Sharing a sentence is not in itself a finding about the gene and the disease. The quoted sentences say what the papers report.
colorectal cancer (2 papers, 2009 to 2011). A primary or metastatic malignant neoplasm that affects the colon or rectum. "In this study, we identified PAPSS2, TUBG2, NTRK2, B4GALT1 and OSMR as genes harboring cancer-specific promoter methylation in human colorectal cancer." (PMID 19662090, 2009).
breast carcinoma (1 paper, 2016). "It is currently unknown, whether TUBG2 plays a role in breast cancer development or progression." (PMID 26621531, 2016).
dementia (1 paper, 2024). Loss of intellectual abilities interfering with an individual's social and occupational functions.
Intellectual disability (1 paper, 2022). "Here, we report the first evidence in favour of TUBG2 as a potential disease gene associated with polymicrogyria and its sequelae of microcephaly, dysplastic corpus callosum, intellectual disability and seizures hat are refractory to treatment." (PMID 36672848, 2022).
nematode infection (1 paper, 2018). "After initial up-regulation, expression of TUBG1 and TUBG2 is significantly down-regulated in mature syncytia, but lack of expression of either of γ-tubulin genes reduces numbers of nematode infections and developing females." (PMID 29947953, 2018). "Herein, we show that although the expression of TUBG1 and TUBG2 genes changes from up-regulation during early stages of syncytium development till down-regulation in mature syncytia, the presence of both γ-tubulin isoforms has fundamental importance for nematode infection and female development." (PMID 29947953, 2018).
polymicrogyria (1 paper, 2022). A developmental brain abnormality characterized by an excessive amount of small convolutions on the surface of the brain and cognitive dysfunction. "Herein, we present an eight-year-old male with bilateral perisylvian polymicrogyria, who was found to have a de novo variant in TUBG2 by exome sequencing." (PMID 36672848, 2022). "In closing, this work provides preliminary evidence that TUBG2 may represent a novel disease gene responsible for polymicrogyria." (PMID 36672848, 2022).
infection (2 papers, 2011 to 2018). The state of being infected such as from the introduction of a foreign agent such as serum, vaccine, antigenic substance or organism. "Transcription analyses demonstrate augmentation of the γ-tubulin (TUBG1 and TUBG2) and two γ-tubulin-complex protein genes (GCP3 and GCP4) in the course of infection with root-knot nematodes in galls." (PMID 22144887, 2011). "Moreover, taking into consideration the lack of TUBG1 and TUBG2 redundancy in infection tests, our novel results rise serious concerns if both γ-tubulin proteins do really play the same roles in plant cells." (PMID 29947953, 2018).
tumor (2 papers, 2009 to 2021). "When methylation values were compared within individual pairs of PN and PT samples, significantly higher methylation levels of PAPSS2 TUBG2, NTRK2, and SFRP4 were found in 60% (18/30), 50% (15/30), 30% (9/30), and 36% (11/30), respectively, in PN than in corresponding tumor samples (PT)." (PMID 19662090, 2009).
cancer (1 paper, 2009). A tumor composed of atypical neoplastic, often pleomorphic cells that invade other tissues. "As a result, we found that 3′-phosphoadenosine 5′-phosphosulfate synthase 2 (PAPSS2), γ-tubulin gene 2 (TUBG2), NTRK2, B4GALT1, and OSMR as well as SFRP4 harbored cancer-specific methylation with high frequencies (>30%)." (PMID 19662090, 2009).
TUBG2 also shares sentences with these, for which no sentence is quoted: cervical cancer (1 paper); depression (1); microcephaly (1); neuroblastoma (1); osteosarcoma (1); prostate carcinoma (1).